SMAD3 (SMAD family member 3)
Diseases named in the same sentence as SMAD3 in open-access papers (continued):
Sharing a sentence is not in itself a finding about the gene and the disease.
pulmonary fibrosis (continued). "Taken together, the findings of our study demonstrated that GGTA significantly attenuated airway inflammation and pulmonary fibrosis by reducing the Th2 cytokines production, accumulation of inflammatory cells and modulating the TGF-β1/Smad-3 signaling pathway." (PMID 27741312, 2016). "Support for this relationship was the finding that in BLM pulmonary fibrosis mouse model, Smad3 was upregulated while miR-29 was downregulated in contrast to results with Smad3–/– mice, which were protected from BLN pulmonary fibrosis and miR-29 was upregulated." (PMID 26106387, 2015). "Through decreasing Smad3/p-Smad3 expression and upregulating miR-140, PTX treatment could significantly reverse the EMT of AECs and prevent pulmonary fibrosis of rats." (PMID 23967091, 2013). "Lack of SMAD3 in mice confers resistance to TGFβ, injury, or inflammation mediated renal and lung fibrosis as well as chemical-induced liver and pancreatic fibrosis." (PMID 21625455, 2011). "Our findings collectively support a model wherein the TGF-β1/SMAD3/ZNF469 axis contributes significantly to ECM gene regulation and fibroblast activation, thereby positioning ZNF469 as a critical profibrotic factor and a promising therapeutic target in pulmonary fibrosis." (PMID 42206677, 2026). "This suggests that Tan IIA inhibits the activation of the TGF-β1/Smad1/Smad3 signaling pathway and activates the Nrf2/antioxidant response element (ARE) signaling pathway, thereby reducing pulmonary inflammation and oxidative stress and slowing pulmonary fibrosis and lung injury." (PMID 40066338, 2025). "Furthermore, ELISA was used to detect pulmonary fibrosis markers COL-1, COL-3, WNT, Vimentin, β-Catenin, Fibronectin, α-SMA, N-Cadherin, E-Cadherin, TWIST, CTGF, FGF2, PDGF-α, MMP2, MMP8, MMP9, MMP13, TIMP1, TGF-β, Smad2, and Smad3 expression levels." (PMID 37812357, 2023). "Hesperidin alleviates BLM-induced IPF via inhibition of TGF-β1/Smad3/AMPK and IκBα/NF-κB pathways which in turn ameliorate the modulation of oxido-inflammatory markers (Nrf2 and HO-1) and pro-inflammatory markers (TNF-α, IL-1β, and IL-6) to reduce collagen deposition during pulmonary fibrosis." (PMID 31611754, 2019). "Therefore, the induced CHRF might inhibit miR-489 expression and consequently derepress the target genes, Smad3, to maintain the TGF-β signaling pathway in silica-induced pulmonary fibrosis." (PMID 29186838, 2017). "However, whether the abnormal expression of Smad3 relates to Smad gene methylation has not been determined, and no study has reported whether pulmonary fibrosis in patients with HP involves the Smad3 and the TGF-β/Smad pathway." (PMID 28562330, 2017). "Our observation provides evidence of SMAD3 nuclear signaling in UIP lesions but not in COP fibroblast plugs and further contributes to the evidence linking the activation of the TGF-β1-SMAD3 axis to the development of pulmonary fibrosis in UIP." (PMID 21660236, 2011).
lung carcinoma (115 papers, 2011 to 2026). "Thereby, in the present study, we explored the mechanisms underlying Smad3-mediated inhibition on GM-CSF production by NK cells as well as how NK-derived GM-CSF sculpted the immune microenvironment in lung carcinoma." (PMID 38878186, 2024). "Not surprisingly, the overexpression of miR-15a caused a significant downregulation of SMAD3 expression and inhibited the proliferation of the A549 lung cancer cell line." (PMID 38279330, 2024). "In experimental lung carcinoma, TANs switch from a predominant N2 state in wild-type mice to an N1 state in Smad3-KO mice which associate with enhanced neutrophil infiltration and tumor regression." (PMID 37002229, 2023). "We have demonstrated a highly effective suppression of LLC lung cancer growth using the Smad3 inhibitor, SIS3, which was associated with increased numbers of TANs and polarization of TANs to a predominant N1 state." (PMID 37002229, 2023). "Although Smad2 and Smad3 are independently recruited to often distinct genomic regions upon TGF-β stimulation in A549 lung cancer cells, the underlying mechanisms of the distinct Smad2 and Smad3 functions remain mostly unclear." (PMID 36549646, 2022). "The EMT that is associated with TGF-β/Smads signaling can be suppressed by lncRNA Smad3-associated long non-coding RNA (SMASR), which are close to Smad3 in lung cancer cells." (PMID 34298613, 2021). "The association of SETDB1 with Smad3 has been also shown to suppress metastasis in lung cancer by repressing IL-2 and the Ca2+-dependent RNA-binding protein annexin A2 (ANXA2) that interacts with the mRNA of the nuclear oncogene, c-myc." (PMID 33803458, 2021). "Our previous study also identified SMAD3: rs11632964 being significantly associated with lung cancer overall survival, which also highlights the important role of SMAD3 in cancer." (PMID 23251617, 2012). "The high expression and deubiquitination of SMAD3 causes poorer prognosis of lung cancer patients." (PMID 40361382, 2025). "MiR-762, MST1, LATS2, YAP mRNA and protein, TWIST1, and SMAD3 may be effective diagnostic biomarkers in both lung cancer patients and chronic inflammatory patients." (PMID 38589525, 2024). "Additionally, SMAD3 promotes the development of lung cancer by influencing lung adenocarcinoma-associated fibroblasts and tumor-associated fibroblasts, which are vital for the tumor microenvironment-driven development of cancer." (PMID 38589525, 2024). "MiR-762, MST1, LAT2, YAP mRNA and protein, TWIST1, SMAD3 may be effective diagnostic biomarkers in both lung cancer patients and chronic inflammatory patients." (PMID 38589525, 2024). "Recently, the research found that TAM might trans-differentiate into cancer-associated fibroblasts in lung carcinoma through a TGF-β/Smad3-dependent pathway known as “macrophage-myofibroblast transition”, as shown by single-cell RNA-sequencing analyses." (PMID 37205317, 2023).
lung carcinoma (continued). "A novel long non‐coding RNA adjacent to SMAD3, named SMAD3‐associated long non‐coding RNA (SMASR), is downregulated by TGF‐β through SMAD2/3 in lung cancer cells." (PMID 39083441, 2025). "The collaboration between Ly6E and α5-nAChR in lung cancer directs TGF-β1/Smad3 signaling, modulating neoplasms migration." (PMID 40143965, 2025). "This study aimed to evaluate the possible correlation between miR-762, the Hippo signaling pathway, TWIST1, and SMAD3 in patients with lung cancer, as well as patients with chronic inflammatory diseases." (PMID 38589525, 2024). "The relative expression of miR-762, MST1, LATS2, YAP, TWIST1, and SMAD3 was determined in 50 lung cancer patients, 30 patients with chronic inflammatory diseases, and 20 healthy volunteers by real-time PCR." (PMID 38589525, 2024). "In lung cancer, the actin-binding protein profilin-2 binds to and thereby prevents HDAC1′s access to the promoters of SMAD2 and SMAD3, which causes activation and promotes EMT and angiogenesis in lung cancer cells." (PMID 38279330, 2024). "Accordingly, this study aimed to evaluate the possible correlations between miR-762, Hippo signaling pathway, TWIST1, and SMAD3 in patients with chronic inflammatory diseases as well as lung cancer patients." (PMID 38589525, 2024). "NSE protein is superior to YAP protein followed by miR-762, MST1, TWIST1, YAP gene, LATS2, and SMAD3 for the prediction of lung cancer." (PMID 38589525, 2024). "Compared to the control group, miR-762, YAP, TWIST1, and SMAD3 expression were significantly upregulated in lung cancer patients and chronic inflammatory patients, except SMAD3 was significantly downregulated in chronic inflammatory patients." (PMID 38589525, 2024). "The survival analyses showed that higher SMAD3 expression was related to lung cancer patients' worse DFS and OS." (PMID 38589525, 2024). "For example, lung cancer metastasis was facilitated by SMYD2-regulated SMAD3 expression in response to TGF-β, while colorectal cancer EMT was inhibited by miR-140 by directly downregulating SMAD3 and deactivating the TGF-β signaling pathway." (PMID 38641828, 2024). "The high frequency of positive SMAD3 phosphorylation in Foxp3-regulatory T cells near CD8+ T cells within the tumour identifies a rapidly progressive lung cancer patient population." (PMID 37685308, 2023). "Downregulation of SMYD2 suppressed the migration and invasion of lung cancer cell lines by reducing SMAD3 expression through SMYD2-mediated epigenetic regulation." (PMID 37121971, 2023). "Meanwhile, SMAD3 can also influence lung cancer progression by affecting the tumour immune microenvironment." (PMID 37685308, 2023). "Here, we found that Gsk3b, Notch2, Pik3cb, Myc, Cdkn1a, and Smad3 were increased in human lung cancer tissue and Cd‐transformed cells, while Pik3cb, Myc, Cdkn1a, and Smad3 were negatively correlated with circCIMT." (PMID 36814305, 2023). "TGF-β1 also suppresses NK cell development in lung cancer and melanoma via a Smad3/erythroid-derived 4 binding protein 4 (E4BP4) axis." (PMID 37205317, 2023). "Here, we show that Smad3-KO neutrophils polarize to an N1 state with a potent antitumor effect in the syngeneic LLC lung cancer model." (PMID 37002229, 2023). "Kaempferol Suppresses Transforming Growth Factor-β1–Induced Epithelial-to-Mesenchymal Transition and Migration of A549 Lung Cancer Cells by Inhibiting Akt1-Mediated Phosphorylation of Smad3 at Threonine-179 (Jo, Park, Choi, Jeon, & Kim, 2015)." (PMID 37533633, 2023). "To model the SMAD2/3 differences observed in TAFs, we stably knocked down SMAD2 or SMAD3 by shRNA in control fibroblasts derived from uninvolved pulmonary tissue of a randomly selected surgical lung cancer patient (#5)." (PMID 36572730, 2023). "Smad3-KO mice exhibit increased neutrophil infiltration and a switch to a predominant N1 antitumor state in a lung cancer model." (PMID 37002229, 2023).
lung carcinoma (continued). "Kaempferol represses TGF-β1-induced metastasis in lung cancer by inactivating AKT1-mediated phosphorylation of Smad3." (PMID 36874921, 2023). "The role of Smad3 in regulating neutrophil recruitment and polarization in lung cancer was investigated in wild-type (Smad3-WT) and Smad3-knockout (Smad3-KO) mice using the syngeneic Lewis lung carcinoma (LLC) cell model." (PMID 37002229, 2023). "We validated the downregulation of SMAD3 by SMYD2 knockdown in lung cancer cell lines by qRT–PCR analysis." (PMID 37121971, 2023). "In an experimental lung cancer mouse model, the TAN in wild-type mice is predominantly in the N2 state, while in SMAD3-KO mice, it shifts to the N1 state, which is associated with enhanced neutrophilic infiltration and tumour regression." (PMID 37685308, 2023). "Profibrotic markers (alpha-smooth muscle actin, fibrillar collagens, SMAD3) expressed in histological samples of patients with lung cancer, are correlated to low survival." (PMID 36733673, 2023). "Mechanistically, they demonstrated that PDLIM5 promotes TGF-β signaling and malignance of lung cancer by specifically interacting with SMAD3 and preventing its degradation." (PMID 36901953, 2023). "Smad3 plays important roles in the cell proliferation, invasion and metastasis of cancer cells, such as lung cancer, colorectal cancer, and chordoma." (PMID 36387210, 2022). "In skin squamous cell carcinoma and non–small cell lung cancer cells, Smad2 suppresses, whereas Smad3 promotes cancer formation, malignant progression, and metastasis." (PMID 36549646, 2022). "Indeed, smoking particles alone can induce the epigenetic repression of SMAD3 in normal pulmonary fibroblasts through increased hypermethylation, which may limit the response to antifibrotic drugs, particularly in lung cancer types strongly associated with smoking such as squamous cell carcinoma." (PMID 34359678, 2021). "miR-136 (miR-136-5p) inhibited mobility, invasiveness, and epithelial–mesenchymal transition in lung cancer cells by targeting Smad2 and Smad3." (PMID 34806748, 2021). "An effect of SMAD3 in smoking induced resistance to chemotherapy as well as the attenuation of the tumor suppression function of TGFbeta in lung cancer has been shown." (PMID 33596996, 2021). "Yet we also found that SMAD3 was transcriptionally repressed through promoter hypermethylation, particularly in SCC, which is a lung cancer subtype strongly associated with smoking." (PMID 34359678, 2021). "KDM4C inhibition reduces the expression of TGF-β2 and decreased the protein levels of p-Smad2 and p-Smad3 in lung cancer cells." (PMID 33558705, 2021). "A similar mechanism (association between Smad3 and SETDB1 to repress gene expression) has also been shown to suppress lung cancer metastasis through repressing ANXA2 expression and repress IL-2 gene expression in activated T cells." (PMID 32114978, 2020). "Our previous study showed that smoking attenuates TGF-β-induced antitumor functions through downregulation of Smad3 in lung cancer cells." (PMID 32668597, 2020). "Our previous study showed that CSC can induce anti-apoptotic gene BCL-2 expression and promote lung cancer cell chemoresistance through downregulating Smad3 expression." (PMID 32668597, 2020). "Our previous study showed that smoking inhibits TGF-β-induced tumor suppressor functions through downregulation of Smad3 in lung cancer cells." (PMID 32668597, 2020). "A previous study has shown that PFN2 promotes the growth and metastasis of lung cancer by epigenetic regulation of Smad2 and Smad3." (PMID 33234737, 2020). "EGCG also inhibits TGF-β1-mediated EMT by suppressing the acetylation of Smad2 and Smad3 in human lung cancer cells." (PMID 31311401, 2019).
lung carcinoma (continued). "TGF-β secreted by TAMs induces EMT and acquisition of cancer stem cells characteristics in an in vitro model of HCC; in lung cancer TAM-secreted TGF-β induces EMT in lung cancer cells by upregulating SOX9 expression via the c-Jun/Smad3 pathway." (PMID 29701666, 2018). "For example, homozygous SMAD3 knockout mice are associated with the overexpression of COX-2, and in A549 human lung cancer cells, TGF-β downregulated the COX-2 expression via mRNA destabilisation through SMAD3." (PMID 30363688, 2018). "For these two genes, there was overlap of HCASMC SMAD3 peaks with some of those identified by ChIPseq in A549 epidermal lung cancer cells, although there were also significant differences in the binding patterns." (PMID 30307970, 2018). "In this study, we found that lung cancer cells promoted the M2 polarization of tumor-associated macrophages (TAMs), which in turn secretes TGF-β and promotes SOX9 expression via the C-jun/SMAD3 pathway, thereby promoting tumor metastasis." (PMID 29245941, 2017). "It was shown that activation of PPAR-γ inhibits TGF-β-induced loss of E-cadherin expression, the induction of mesenchymal markers (vimentin, N-cadherin, fibronectin), MMPs and antagonizes Smad3 function, thereby preventing metastasis in lung cancer." (PMID 27092172, 2016). "In lung cancer cells, transcription factors, such as SMAD3, have been reported to constitute SEs." (PMID 41614901, 2026). "Notably, a parallel mechanism was reported in lung cancer, where PSMD14 promotes metastasis by deubiquitinating Smad3 to augment TGF-β1/Smad3 signaling and is associated with poor patient prognosis." (PMID 41488674, 2025). "Notably, nicotine elicits an upregulation of α5-nAChR, Ly6E, phosphorylated Smad3 (pSmad3), Zeb1, N-calmodulin, and vimentin in lung cancer cells." (PMID 40143965, 2025). "The transcription factor suppressor of mothers against decapentaplegic homolog 3 (SMAD3) plays a decisive role in shaping the epigenetic profile of CAFs and its targeting with the potent and selective SMAD3 inhibitor SIS3 has demonstrated significant efficacy in preclinical lung cancer models." (PMID 40092694, 2025). "Additionally, MSI2 promotes increased invasion of lung cancer cells by regulating the TGFβR1/SMAD3 signaling pathway, which can be used as an effective biomarker for the prognosis of NSCLC." (PMID 39969091, 2025). "SMAD3 accelerates the growth of lung cancer by affecting downstream factors." (PMID 38589525, 2024). "Consistent with lung carcinoma cells 102, Smad3 deletion similarly inhibited the process of EMT." (PMID 38818471, 2024). "(B) Enhancer action: Zhang and colleagues showed that M2-like tumor-associated macrophages (TAM2) infiltration facilitates a rich TGFβ microenvironment and promotes SMAD3 binding to the enhancer of Linc01977, therefore initiating malignancy through the TGFβ/SMAD3 pathway in lung cancer." (PMID 39443468, 2024). "Furthermore, silencing GM-CSF in Smad3 knockout NK cells substantially impaired their anti-lung carcinoma effects." (PMID 38878186, 2024). "Thus, inhibition of Smad3 is identified as a therapeutic strategy to promote polarization of TANs to an antitumor N1 state and thus suppress the development of lung cancer." (PMID 37002229, 2023). "Here the authors show that Smad3 activation in TANs is associated with an N2-like polarization state and poor outcome in patients with non-small cell lung carcinoma and that Smad3 targeting reprograms TANs to an antitumor state suppressing tumor growth in preclinical lung cancer models." (PMID 37002229, 2023). "Moreover, SMAD3 knockdown suppresses the migration and invasion of lung cancer cell line, and the expression of VIM and CDH2 was decreased by SMAD3 knockdown." (PMID 37121971, 2023). "To further substantiate the function of N1 Smad3-KO neutrophils in lung cancer development, we performed adoptive transfer studies, which showed that delivery of Smad3-KO-BMDN, but not wild-type BMDN, could suppress tumor growth." (PMID 37002229, 2023).